CRP (C-reactive protein)
Diseases named in the same sentence as CRP in open-access papers (continued):
Sharing a sentence is not in itself a finding about the gene and the disease.
sarcopenia (398 papers, 2010 to 2026). Progressive decline in muscle mass due to aging which results in decreased functional capacity of muscles. "The meta‐analysis showed that a per 1 mg/L increase in CRP was significantly associated with a higher risk of sarcopenia overall (crude OR = 1.09; 95% CI: 1.00–1.19; I2 = 29.7%; p = 0.034; adjusted OR = 0.66; 95% CI: 0.10–4.16; I2 = 95.8%; p = 0.655)." (PMID 41457350, 2026). "On the left side of the threshold, the Hs-CRP/HDL-C ratio was significantly associated with increased odds of sarcopenia (OR=4.34, 95% CI: 1.98-9.52, p<0.001)." (PMID 40672942, 2025). "Systemic inflammatory markers such as C-reactive protein (CRP) and interleukin-1β (IL-1β) are elevated in individuals with sarcopenia, indicating a strong association between inflammation and muscle loss." (PMID 40943447, 2025). "A cross-sectional study showed that a lower body BMI at initial assessment and higher levels of CRP at enrollment were associated with sarcopenia." (PMID 40095540, 2025). "Loneliness not only affects the mental health of older people but can also induce inflammatory responses, leading to increased interleukin-6 and C-reactive protein levels, which are potential risk factors for sarcopenia." (PMID 41013236, 2025). "In our study, CRP was initially associated with sarcopenia in unadjusted models, but this relationship weakened after adjusting for confounders." (PMID 40708651, 2025). "Meta-analyses have shown that elevated CRP and Hs-CRP levels are significantly associated with reduced muscle strength and mass, supporting a link between systemic inflammation and sarcopenia." (PMID 40672942, 2025). "According to a recent meta-analysis, sarcopenia affects 22% of patients with SSc and is associated with poorer quality of life and greater CRP levels." (PMID 40422566, 2025). "The dose–response relationship between CRP and possible sarcopenia risk was visualized using RCS curves." (PMID 40791098, 2025). "A multicenter, cross-sectional study including 209 HD patients showed that sarcopenia was closely associated with increased high-sensitive CRP levels." (PMID 40142260, 2025). "Recent studies also suggest a significant association between high CRP and sarcopenia in cancer patients." (PMID 40539144, 2025). "Participants in the highest quartile (≥2.75) of the Hs-CRP/HDL-C ratio had a 122% higher risk of sarcopenia compared to those in the lowest quartile (p=0.005)." (PMID 40672942, 2025). "A meta-analysis focused on rheumatoid sarcopenia revealed that certain disease-related factors, including radiological joint damage, elevated CRP levels, and the presence of RF, significantly contribute to the risk of developing sarcopenia." (PMID 40282842, 2025). "The findings indicated a significant association, showing that patients with sarcopenia had higher CRP levels." (PMID 40095540, 2025). "In higher CRP and BMI groups, DR-only positive males and typical positive females retained heightened sarcopenia risk." (PMID 41041314, 2025). "The threshold effect analysis of the Hs-CRP/HDL-C on sarcopenia risk among adults in NHANES 2013–2018." (PMID 40672942, 2025). "A cutoff point at log CRP = 0.99 divided the plot into two phases: for log CRP < 0.99, possible sarcopenia risk increased rapidly (OR: 1.41, 95% CI: 1.30–1.52; cutoff point log CRP = 0.99 vs." (PMID 40791098, 2025). "In order to develop early detection and intervention for sarcopenia, it is essential to establish a definitive correlation between CRP levels and sarcopenia risk." (PMID 39502753, 2024). "Several studies revealed that sarcopenia risk increases with circulating cytokines, such as CRP, IL-10, growth differentiation factor-15, and TNF-α." (PMID 39345889, 2024). "The study revealed an association between sarcopenia and serum CRP levels as well as DAS28 scores, both of which are correlated with reduced skeletal muscle mass and strength." (PMID 39136015, 2024).
sarcopenia (continued). "We evaluated the extent to which CRP levels are associated with the risk of sarcopenia using both univariate and multivariate logistic regression models." (PMID 39502753, 2024). "According to the probability plot of logistic regression, it can be observed that the risk of sarcopenia increases in proportion to the elevation in CRP levels." (PMID 39502753, 2024). "In conclusion, our findings demonstrate a robust association between the levels of CRP and the initiation of sarcopenia." (PMID 39502753, 2024). "Sensitivity and subgroup analyses were used to control for the impact of potential confounders on the association of CRP levels with sarcopenia." (PMID 39969369, 2024). "Mediation analyses were undertaken to assess if the association between the MAFLD and sarcopenia were mediated by CRP and serum lipids." (PMID 38491346, 2024). "Population data have indicated that IL-6 and tumor necrosis factor α levels are significantly increased in older adults with sarcopenia; the higher the levels of IL-6 and C-reactive protein, the greater the risk of muscle loss." (PMID 39390392, 2024). "In spite of this limitation, our investigation employed the dependable indicators of sarcopenia, including grip strength, walking pace, and ALM, to furnish compelling proof endorsing an inverse cause-and-effect connection between CRP and sarcopenia." (PMID 39502753, 2024). "Our study uncovered strong evidence supporting a noteworthy inverse association and causality between CRP concentrations and sarcopenia, indicating that CRP has the potential to serve as a biomarker for sarcopenia." (PMID 39502753, 2024). "Association between CRP level and sarcopenia among adult participants in the NHANES 2015 to 2018 cycles." (PMID 39969369, 2024). "Owing to its cross-sectional nature, it was impossible to determine the causal relationship between CRP levels and sarcopenia." (PMID 39969369, 2024). "Our study also showed that albumin level and inflammation markers (CRP and FC) were associated with sarcopenia in univariable analysis." (PMID 38438954, 2024). "Some studies also showed the associated factors for sarcopenia in CD patients, such as nutrition-related indicators (Low albumin level) and higher levels of inflammatory markers (CRP, ESR, and FC)." (PMID 38438954, 2024). "Lower albumin, sodium, and platelet levels, in addition to high values of CRP, were also linked to higher mortality in all groups, with the greatest impact in the group with both sarcopenia and frailty." (PMID 39795544, 2024). "In particular, the risk of sarcopenia increased with increasing CRP levels in those with the CRP levels > 1.8." (PMID 39969369, 2024). "Accelerated sarcopenia has also been implicated with age, visceral adiposity, albuminuria, osteoporosis, nephropathy and higher C-reactive protein (CRP)." (PMID 39449093, 2024). "Logistic regression analyses identified CRP as an independent risk factor for sarcopenia (OR: 1.151, 95% CI:1.070−1.238, and P < 0.001)." (PMID 39502753, 2024). "A meta‐analysis revealed that sarcopenia (which is known to be accompanied by increased of muscle fibrosis) seems to be associated with elevated serum CRP levels." (PMID 38652110, 2024). "Odds ratios (OR) and 95% confidence intervals (95% CI) were determined using multivariable logistic regression to analyze the association between CRP levels and sarcopenia." (PMID 39969369, 2024). "The onset of sarcopenia is strongly linked to elevated CRP levels, as revealed by our research findings." (PMID 39502753, 2024). "Considering these factors, our study was designed to comprehensively investigate the association between CRP levels and sarcopenia." (PMID 39502753, 2024). "Sarcopenia is associated with interleukin-6 (IL-6) and C-reactive protein (CRP), which are markers of inflammation." (PMID 38233827, 2024). "Sarcopenia and sarcopenic obesity were also positively associated with CRP (p < 0.05 for both cases)." (PMID 37960189, 2023).
sarcopenia (continued). "Our study found an association between sarcopenia and certain inflammatory mediators as CRP, albumin, CRP/albumin ratio, IL-1β, and cfDNA." (PMID 37465171, 2023). "The results showed that age, BMI, ALD, CRP, total cholesterol, and serum sodium level were independent factors associated with sarcopenia in patients with CLD." (PMID 38024081, 2023). "IL-6, TNFα, and CRP are also strongly upregulated in primary sarcopenia, suggesting a causal role of inflammageing in muscle loss." (PMID 35276842, 2022). "Two recent meta-analyses have been conflicting regarding TNF-α and IL-6, but both conclude elevated CRP is associated with sarcopenia." (PMID 36465176, 2022). "A vast array of studies has shown that elevated serum CRP levels are associated with sarcopenia and frailty." (PMID 36261756, 2022). "Although the mechanistic link between CRP elevation and sarcopenia is still unclear, there are in vitro studies supporting the role of chronic elevation of CRP in aging-related diseases and muscle mass loss." (PMID 35570546, 2022). "BMI at the onset of SSc and C-reactive protein > 5 mg/dL were significantly associated with sarcopenia with a respective OR of 0.60 (95% CI 0.48–0.75) and 3.18 (1.06–9.54)." (PMID 36307496, 2022). "SSc patients with a low BMI and a high CRP are at risk of sarcopenia and should be monitored closely." (PMID 36307496, 2022). "It has been shown that elevation of IL-6 and CRP especially play a role as a possible inflammatory link between sarcopenia and cardiovascular risk." (PMID 35682063, 2022). "Herein, we developed and validated a simple nomogram to predict the risk of developing sarcopenia in HD patients with a total of five clinically relevant variables, including age, C-reactive protein, serum phosphorus, BMI, and MAMC." (PMID 36138351, 2022). "In conclusion, elevated levels of TNF-α are significantly associated with the risk of sarcopenia, while variations perceived in circulating CRP can be explained by changes in the muscle mass indices only among individuals with sarcopenia." (PMID 36291982, 2022). "On the other hand, elderly with sarcopenia had higher levels of hs-CRP and a higher risk of arteriosclerosis." (PMID 36079726, 2022). "Sarcopenia and high CRP level were independently associated with PFS of erlotinib as poor prognostic factors." (PMID 35575465, 2022). "The study demonstrated that high hs-CRP levels are associated with slow gait speed and low muscle mass, which in turn lead to the development of sarcopenia in older adults." (PMID 35570546, 2022). "Elevated CRP, in general, is associated with other conditions characterized by muscle wasting such as sarcopenia, cachexia, and frailty." (PMID 35719155, 2022). "Recently sarcopenia, measured by reduced hand grip strength, and associated with the type of vasculitis, severity and high C-reactive protein (CRP), seemed to predict increased fracture risk." (PMID 35250864, 2022). "Our study revealed that low BMI at onset and high CRP at enrollment were associated with sarcopenia." (PMID 36307496, 2022). "Sarcopenia and systemic inflammation commonly coexist, and the net skeletal muscle protein balance was found negatively associated with hs-CRP in patients with CKD." (PMID 35634405, 2022). "In this study, we found that sarcopenia was associated with low height-for-age, low BMI-for-age, high levels of inflammatory markers such as CRP and ESR, and low levels of hemoglobin, hematocrit, and albumin in 105 children diagnosed with primary CD." (PMID 35608430, 2022). "An elevated TNF-α is associated with a higher risk of sarcopenia, while variances perceived in other inflammatory markers, such as CRP, are associated with select muscle indices found only among elderly women with sarcopenia." (PMID 36291982, 2022). "The high concentration of CRP was related to high risk of possible sarcopenia (OR 1.02; 95% CI 1.01–1.03)." (PMID 33661964, 2021).
sarcopenia (continued). "Multivariate analysis showed that abnormal values of CRP (OR 5.1), severe anxiety (OR 3.7) and sarcopenia (OR 4.4) were the factors independently associated with severe fatigue." (PMID 34315951, 2021). "Second, sarcopenia is associated with inflammatory indicators, such as the C-reactive protein level and the neutrophil-to-lymphocyte ratio." (PMID 34778314, 2021). "In subgroup analysis, CRP was positively associated with sarcopenia in those aged ≥70 years (p-trend = 0.04) or with multimorbidity (p-trend = 0.02)." (PMID 34836213, 2021). "A systematic review and meta-analysis conducted in 2016 observed a correlation between significantly higher levels of CRP and sarcopenia (defined as muscle mass loss)." (PMID 33566325, 2021). "Our multivariate model suggests that sarcopenia, altered CRP and severe anxiety were the only independent risk factors for severe fatigue." (PMID 34315951, 2021). "Factors associated with sarcopenia in this study were age (OR = 1.08, p = 0.008), BMI (OR = 0.73, p < 0.001), CRP (OR = 1.76, p = 0.017), and hip bone mineral density (BMD) (OR = 0.61, p = 0.037)." (PMID 33566325, 2021). "Logistic regression analysis was performed to examine the association between sarcopenia and inflammatory markers (logarithm of hs-CRP and WBC)." (PMID 32706758, 2020). "For example, pooling data from 16 studies showed that sarcopenia was associated with a higher level of CRP." (PMID 33160322, 2020). "Sarcopenia is also associated with inflammation, and with the increased levels of inflammatory markers CRP and IL-6." (PMID 33318308, 2020). "We also evaluated inflammatory biomarkers of sarcopenia including homocysteine, CRP, NLR and vitamin D. Severe vitamin D deficiency was similar in all groups." (PMID 33187310, 2020). "Sarcopenia and loss of muscle strength have been associated with increased serum concentrations of inflammatory markers, including IL-6, CRP, and TNF-alpha." (PMID 31590379, 2019). "In general, as discussed in a recent meta-analysis article, sarcopenia seems to be associated with elevated serum CRP levels." (PMID 30115813, 2018). "We found that a higher CRP was associated with lower grip strength, accelerated loss of grip strength, slower gait speed (in gender-adjusted analyses only), and sarcopenia (in fully-adjusted analyses only)." (PMID 29101476, 2018). "A meta-analysis of 17 cross-sectional studies has reported that inflammatory cytokines, particularly CRP, were positively associated with the risk of sarcopenia in participants with a mean age of 66 years." (PMID 30249038, 2018). "In multivariable logistic regression model, age, gender, BMI, eGFR, DM, CRP, and overall diuretic use (particularly loop diuretic use) were significantly associated with sarcopenia." (PMID 29447254, 2018). "An increased risk of sarcopenia was also observed in patients with higher CRP and in patients with disabilities (OR = 3.2; 95% CI: 1.2–8.3, p = 0.01 and OR = 4.5; 95% CI: 1.8–11.2, p = 0.001, respectively)." (PMID 30513782, 2018). "For individual CRFs, we found that high levels of CRP were associated with mobility limitation, possibly by the role of inflammation in the aging-related process that leads to sarcopenia and loss of muscle strength." (PMID 23741513, 2013). "Thirteen studies reported the association between CRP and sarcopenia in patients with CKD." (PMID 41457350, 2026). "Three studies reported the association between hs‐CRP and sarcopenia in patients with CKD." (PMID 41457350, 2026). "Future studies could explore whether metabolic health parameters, such as HbA1c, CRP, the lipid profile, protein levels, as well as the risk of sarcopenia, are more predictive of THA outcomes than weight loss alone." (PMID 41574211, 2026).
sarcopenia (continued). "In men, sarcopenia was associated with higher CRP levels, lower albumin and GNRI scores, and a greater prevalence of vascular complications, whereas in women, it was related to lower waist circumference, albumin levels, and handgrip strength, as well as a higher frequency of retinopathy." (PMID 41393007, 2025). "In addition, high levels of CRP are associated with losing muscle strength and are seen as a good indicator of inflammatory status for investigating sarcopenia." (PMID 40943447, 2025). "Moreover, a cross-sectional study involving individuals aged 90 years and older revealed that interleukin-6 (IL-6), interleukin-1 receptor antagonist (IL-1Ra), and C-reactive protein (CRP) were correlated with the risk of sarcopenia." (PMID 40735206, 2025). "Studies have shown that elevations in IL-6 and CRP may particularly play a role in the inflammatory link between sarcopenia and cardiovascular risk." (PMID 40034988, 2025). "Furthermore, apelin implicated in sarcopenia and inflammatory biomarkers (CRP, TNF-α, IL-6, IL-8, and LTB4) were also measured in the serum." (PMID 40649397, 2025). "Moreover, the following study found that sarcopenia was associated with higher serum CRP levels, regarding the relationship between frailty and inflammation." (PMID 40141756, 2025). "Additionally, a two-step MR analysis was used to assess the mediating effect of CRP in the causality between sarcopenia and HCC." (PMID 38860158, 2024). "Additionally, our cohort revealed that sarcopenia was linked to advanced age, serum albumin levels, and CRP levels, aligning with earlier studies." (PMID 39315011, 2024). "CRP, as an inflammatory biomarker, can indicate the presence of underlying systemic inflammation that may accelerate the progression of sarcopenia." (PMID 39502753, 2024). "In addition, the association between CRP levels and sarcopenia was robust in the subgroup and sensitivity analyses." (PMID 39969369, 2024). "Moreover, numerous studies have found that inflammatory markers detected in blood tests, including the Systemic Immune-Inflammation Index (SII), C-reactive protein (CRP), and interleukin-17, are closely associated with sarcopenia." (PMID 39556533, 2024). "In this study, it was shown that the CRP levels were associated with sarcopenia in males (OR, 1.03; 95% CI, 1–1.05), individuals aged <50-year-old (OR, 1.03; 95% CI, 1.01–1.05), drinking (OR, 1.02; 95% CI, 1–1.03), and BMI ≥ 25 kg/m2 (OR, 1.02; 95% CI, 1–1.03)." (PMID 39969369, 2024). "Additionally, our correlation analysis revealed a substantial inverse association linking the levels of CRP in serum and critical factors associated with sarcopenia, including strength of grip, ALM, and velocity while walking a distance of 6 m." (PMID 39502753, 2024). "It was suggested that diffuse SSc was associated with inflammation (higher levels of CRP), which could lead to cachexia and sarcopenia syndromes." (PMID 39203760, 2024). "Moreover, we have employed the Mendelian randomization (MR) analysis technique to explore the causal relationship between CRP levels and the occurrence of sarcopenia." (PMID 39502753, 2024). "In addition, the progression of aging and the development of sarcopenia are strongly associated with elevated levels of CRP and a reduced BMR." (PMID 39764251, 2024). "Our study aimed to investigate the causal link between CRP and sarcopenia." (PMID 39502753, 2024). "Also, basic research suggests that inflammatory markers and hormonal pathways (interleukin-6, C-reactive protein, myokines, and serum testosterone) play a role in the association between sarcopenia and cognitive impairment." (PMID 38613024, 2024). "By monitoring CRP levels, clinicians can identify individuals at risk early in the course of sarcopenia, enabling the timely implementation of therapeutic strategies aimed at reducing inflammation, thereby preserving muscle function and improving clinical outcomes in aging populations." (PMID 39502753, 2024).